CD36 (CD36 molecule (CD36 blood group))
Diseases named in the same sentence as CD36 in open-access papers (continued):
Sharing a sentence is not in itself a finding about the gene and the disease.
leukemia (23 papers, 2017 to 2025). A malignant (clonal) hematologic disorder, involving hematopoietic stem cells and characterized by the presence of primitive or atypical myeloid or lymphoid cells in the bone marrow and the blood. "The higher frequency of CD36-positive cells at diagnosis was identified in cases that presented recurrence of the disease, as well as a higher risk of relapse for CD36+ patients, thereby presenting a shorter leukemia-free survival rate." (PMID 40527069, 2025). "Five-year non-survivors showed increased levels of CD36-positive AML blasts, while complete remission was achieved in a higher percentage of CD36-nagative patients, as well as overall survival rates and leukemia-free survival rates." (PMID 40527069, 2025). "CD36 mediates the IL-6-driven resistance against standard chemotherapeutic agents through elevated fatty acid uptake in leukemia cells." (PMID 37256177, 2023). "CD36+ LSCs are characterized by an enhanced FAO rate, and disruption of mitochondrial metabolism by targeting CD36-FAO-OXPHOS drives leukemia cells to low OXPHOS and enhances AraC sensitivity." (PMID 37842232, 2023). "For instance, leukemia stem cells with a high CD36 expression level have been shown to be resistant to cytarabine, doxorubicin, etoposide, SN38, and irinotecan." (PMID 37371076, 2023). "In acute myeloid leukemia (AML), we found that APOC2 acts with CD36 to promote leukemia growth by activating the LYN-ERK signaling." (PMID 37226083, 2023). "CD36 expression correlates with unfavorable cytogenetics, shorter overall survival, and a shorter leukemia free survival." (PMID 36568966, 2022). "Previous reports also describe the expression of CD36 in megakaryocyte lineage leukemias, but the stage of megakaryocytes’ maturation is still unclear." (PMID 36409726, 2022). "CD36 is a fatty acid translocase that takes up substrates for mitochondrial fatty acid oxidation and is expressed on leukemia stem cells." (PMID 33948920, 2021). "In line with this, adipocytes located in gonadal tissue play a supportive role in CD36 + AML leukaemia stem cell (LSC) maintenance and expansion." (PMID 34535653, 2021). "In another study, CD36-positive leukaemia cells were shown to be relatively more drug-resistant to AraC in vivo and in vitro compared with CD36-negative cells." (PMID 30319689, 2018). "Importantly, the genetic ablation of CD36 in leukemia cells abrogated gonadal adipose homing and conferred sensitization to chemotherapy." (PMID 37371076, 2023). "In addition, studies in leukemia models showed that the FA6.152 monoclonal anti-CD36 or the CD36 inhibitor SSO, when used in conjunction with chemotherapy drugs such as Ara-C or doxorubicin, led to a significant extension in survival." (PMID 37700339, 2023). "Lastly, leukemia stem cells exhibiting a high CD36 expression level and elevated rates of FA oxidation (FAO) have been shown to preferentially home to gonadal adipose tissue, indicating a preference for lipid-rich microenvironments that facilitates their FA needs." (PMID 37371076, 2023). "APOC2 also promotes the growth of leukemia through the CD36‐ERK signaling." (PMID 34459127, 2021). "CD36-positive leukaemia stem cells were shown to have elevated FA uptake and ß-oxidation." (PMID 30319689, 2018). "Other work indicates that decitabine can enhance CD36-mediated immunosuppression in leukemia cells, leading to chemotherapy resistance, whereas statins may improve decitabine efficacy by reducing lipoproteins transported via CD36 and thereby alleviating immunosuppression." (PMID 41295305, 2025). "In leukemia, LGALS1 upregulates the expression of genes involved in lipid uptake (such as CD36) and de novo lipogenesis (such as PPARγ, FASN, and ACC), thereby enhancing lipid accumulation." (PMID 40881692, 2025). "This suggests a potential role of CD36 and CD73 in promoting leukemia development within such an adipocytic microenvironment." (PMID 40285538, 2025).
leukemia (continued). "Various surface markers, such as CD93, CD69, and CD36, have been found to demarcate distinct subpopulations of immunophenotypically sorted HSC-like cells (CD34+CD38−) that differ in leukemia initiating activity and cell cycle status." (PMID 37653425, 2023). "CD36-mediated lipid accumulation provides ATP through FAO, which energizes the machinery responsible for manifesting resistance in leukemia cells." (PMID 37256177, 2023). "CD36-positive patients with trisomy 8 had significantly poorer leukemia-free survival compared to CD36-positive patients without trisomy 8,30 highlighting the interplay between CD36 and specific cytogenetic alterations." (PMID 40527069, 2025). "In vivo APOC2 and CD36 knockdown reduces leukemia burden and engraftment to bone marrow, spleen, and peripheral blood; therefore APOC2-CD36 signaling may be an attractive therapeutic target." (PMID 36568966, 2022). "Relevant to the connection between oncogenic STAT3 and aberrant lipid metabolism, it has been shown that STAT3-activated CD36 contributes to fatty acid uptake in chronic lymphocytic leukemia cells, which supports a critical role of STAT3 in the regulation of CD36-dependent leukemia." (PMID 33718197, 2021).
liver fibrosis (22 papers, 2013 to 2026). "CD36 polymorphism (rs1761667) is associated with higher fat intake and more instances of advanced liver fibrosis in chronic HCV infection." (PMID 39774047, 2025). "In addition, ligand-receptor pair analysis revealed that aHSC could interact with hepatocytes and Cd36+ KCs via the Lamb2/Dag axis, which have been demonstrated to be associated with liver fibrosis." (PMID 39494341, 2024). "In this study, we found that CD36 was markedly upregulated in NK cells from mice with liver fibrosis." (PMID 42220492, 2026). "As summarized above, CD36 has multiple roles in fat accumulation, liver inflammation, and viral replication, as well as in promoting liver fibrosis and liver cancer progression." (PMID 39774047, 2025). "Although 6-week MCD diet feeding caused moderate liver fibrosis, sirius red staining data indicate that liver fibrosis was more severe in MCD-fed CD36−/− mice compared to MCD-fed wild-type mice." (PMID 40110132, 2025). "Recent animal experiments indicate that CD36 in hepatocytes can exert a protective effect against liver fibrosis and injury by blocking the production of N1ICD." (PMID 39774047, 2025). "Overall, our data identified MST1 as a novel regulator for egg-induced liver fibrosis via modulation of macrophage function and phenotype by CD36-mediated phagocytosis and suppression of NF-κB pathway." (PMID 39700261, 2024). "In contrast to LyECs, Mcam, Fcgr2b (CD32b), Cxcl9, CD36, Kit, Clec4g, etc., genes were highly expressed in LSECs from CCl4-induced liver fibrosis, NASH and BDL mice." (PMID 36632228, 2023). "Mounting evidence suggests that miRNA-29a inhibits CD36 and improves steatohepatitis and liver fibrosis induced by a high-fat diet in mice." (PMID 34867446, 2021). "The adoptive transfer of CD36- NK cells alleviated liver fibrosis progression." (PMID 42220492, 2026). "In conclusion, CD36 might play a key role in promoting liver fibrosis, and targeting CD36 could be a potential strategy to halt the progression of liver fibrosis." (PMID 39774047, 2025). "Through CD36-mediated phagocytosis, macrophages undergo a phenotypic transition from a pro-inflammatory and profibrotic phenotype to one that actively facilitates the resolution of fibrosis, thereby protecting against schistosomiasis-induced liver fibrosis." (PMID 39700261, 2024). "Our study demonstrated that LCFA facilitates hepatocyte activation by up-regulating oxidative stress through CD36, which could be an important mechanism in the development of hepatic fibrosis." (PMID 30016988, 2018). "In addition, we conducted to assess the impact of CD36 on liver fibrosis." (PMID 40110132, 2025). "Therefore, targeting key nodes within the macrophage metabolic-signaling network—such as PPARγ/CD36, Foxo1 phosphorylation, mitophagy, and glycolytic enzymes—may offer multi-mechanism therapeutic strategies for liver fibrosis." (PMID 41459510, 2025). "Specifically, MST1 kinase enhances the PPARγ/CD36 pathway to improve phagocytic function, upregulate fibrolytic genes including Arg1 and Mmps, and suppress the NF-κB signaling pathway, ultimately ameliorating schistosome egg-induced granulomas and liver fibrosis." (PMID 41459510, 2025). "CD36 is highly expressed in monocytes/macrophages infiltrating fibrotic livers, suggesting that highly CD36-expressing monocytes recruited to the liver may exacerbate hepatic fibrosis." (PMID 40725208, 2025). "Moreover, liver fibrosis was exacerbated in the liver of MCD diet-fed CD36−/− mice." (PMID 40110132, 2025). "iPSC-derived hepatocytes from normal and obese subjects are cultured to assess their lipid accumulation, via hepatic fibrosis pathways, by running transcriptome analyses to compare gene expression associated with hepatic fibrosis (caveolin 1 (CAV1) and cluster of differentiation 36 (CD36))." (PMID 40801620, 2025).
liver fibrosis (continued). "CD36 can mediate oxidative stress in hepatocytes, and LCFAs induce hepatocyte activation through the oxidative stress pathway, which may be an important mechanism in the process of liver fibrosis." (PMID 39774047, 2025). "Among other genes, increased CD36 and CAV1 expression and decreased expression of CES1 in obese iPSCs could have been responsible for excess lipid accumulation, resulting in differential expression of genes associated with hepatic fibrosis, a key feature of non-alcoholic fatty liver disease (NAFLD)." (PMID 35915082, 2022). "Herein, our study shows that miR-29a overexpression exerts protective effect in HFD-elicited CD36 expression, EMT, and liver fibrosis." (PMID 31652636, 2019). "Given the prior literatures about liver fibrosis suggesting that COMP induced fibrillary collagen-I deposition via CD36 receptor, we wonder if CD36 was related with COMP in HCC." (PMID 30231922, 2018). "Accumulating evidence suggests that CD36 plays a complex role in the development of nonalcoholic simple fatty liver disease and NASH and contributes to the pathogenesis of inflammatory liver injury, hepatitis B/hepatitis C, liver fibrosis, and liver cancer." (PMID 39774047, 2025). "Modulating intestinal absorption of PA by regulating CD36, MTP, and GLP-2 expression may reduce liver inflammation and inhibit the progression of liver fibrosis in NASH." (PMID 34183709, 2021). "Our previous study showed that Cyp4a14 is activated in mice suffering from MCD-induced liver fibrosis, and Cyp4a14–/– mice could attenuate the MCD-induced liver fibrosis, accompanied by reduced hepatic FAT/CD36 expression." (PMID 34135776, 2021). "Increased KLF6 expression augments enhanced collagen 1 and TGFß1 expression to result in liver fibrosis, and overexpression of KLF2 induces expression of the fatty acid translocator CD36 whereas KLF15 plays an essential role in ER stress-mediated insulin resistance in the liver." (PMID 29296203, 2017). "MiR-29a could target CD36 to ameliorate HFD-induced steatohepatitis and liver fibrosis in mice." (PMID 39774047, 2025). "Therefore, we wondered whether CD36 mediates S100A8-induced ROS production and NF-κB pathway activation in liver fibrosis progression, which requires further studies to investigate." (PMID 36429008, 2022).
acute myeloid leukemia (21 papers, 2018 to 2025). Acute myeloid leukemia (AML) is a group of neoplasms arising from precursor cells committed to the myeloid cell-line differentiation. "CD36 is a glycoprotein associated with resistance to chemotherapy and the recurrence of acute myeloid leukemia." (PMID 40527069, 2025). "According to this systematic review, CD36 is associated with different prognostic factors in acute myeloid leukemia, including remission and relapse of the disease, overall survival, and chemoresistance." (PMID 40527069, 2025). "It has also been reported that high expression of CD36 contributes to an increased recurrence rate in pancreatic ductal adenocarcinoma and acute myeloid leukemia." (PMID 41465497, 2025). "This systematic review aims to evaluate the impact of CD36 on the prognosis of acute myeloid leukemia, a complex heterogeneous malignant hematopoietic disease." (PMID 40527069, 2025). "Currently, CD36 has proven to be a key player in the progression of leukemia, such as acute myeloid leukemia (AML) and chronic myeloid leukemia (CML)." (PMID 41550652, 2025). "The exogenous lipid transporter CD36, by activating NF-κB, induces the expression of immunosuppressive genes, thereby facilitating immune evasion in acute myeloid leukemia (AML)." (PMID 41245411, 2025). "Similarly, acute myelogenous leukemia (AML) patients with high expression of CD36 also had worse prognoses." (PMID 40514365, 2025). "In this regard, chemotherapy-resistant acute myeloid leukemia (AML) cells exhibit increased expression of FA transporter CD36, along with enhanced FAO and OXPHOS." (PMID 41439977, 2025). "In acute myeloid leukemia (AML) patients, CD36 was highly expressed in tumors with an advanced stage." (PMID 36568966, 2022). "It has been previously reported that APOC2 interacts with CD36 to trigger downstream signaling in acute myeloid leukemia (AML) and atherosclerosis." (PMID 34459127, 2021). "Additionally, acute myeloid leukemia (AML) cells uptake exogenous palmitate via CD36, activating ZDHHC6-mediated MYD88 palmitoylation to potentiate the TLR4-LYN-MYD88-NF-κB signaling axis." (PMID 40977744, 2025). "Bone marrow immunophenotypic analyses revealed 23% blasts; positivity for CD34, HLADR and CD33; and negativity for CD7, CD19, CD10, CD117, CD36 and CD15, characterizing acute myeloid leukemia (AML), FAB classification M4." (PMID 28832804, 2018).
endothelial dysfunction (21 papers, 2013 to 2025). In vascular diseases, endothelial dysfunction is a systemic pathological state of the endothelium (the inner lining of blood vessels) and can be broadly defined as an imbalance between vasodilating and vasoconstricting substances produced by (or acting on) the endothelium. "Humans carrying the minor allele (G) of CD36 coding variant rs3211938 have 50% reduced CD36 expression and show endothelial dysfunction." (PMID 39503770, 2025). "Collectively, our findings suggest that synthetic peptides targeting CD36 hold strong therapeutic potential in mitigating aging-associated endothelial dysfunction and improving lung inflammatory syndromes in aging populations." (PMID 37566016, 2023). "As a result, glycolytic intermediates are diverted to form advanced glycation end-products, which can be recognized by CD36 causing oxidative stress-related inflammation and endothelial dysfunction." (PMID 35786219, 2022). "The analysis of differentially expressed genes showed that some genes associated with endothelial dysfunction were significantly upregulated, such as CD36, EDN1, ANGPT2 and so on." (PMID 36091033, 2022). "Disruption of PPARγ signaling can lead to altered expression of genes involved in lipid metabolism, such as fatty acid binding protein 4 (FABP4) and CD36, contributing to the development of a pro-inflammatory state and endothelial dysfunction." (PMID 39062815, 2024). "As the major endothelial fatty acid translocase, endothelial CD36 was previously shown to be required for tissue utilization of fatty acids, yet its role in mediating endothelial dysfunction remains to be resolved." (PMID 38586877, 2024). "High glucose conditions can exacerbate oxidative stress and calcification through the induction of CD36 scavenger receptors and endothelial dysfunction." (PMID 37180797, 2023). "CD36 pathways are activated by several distinct ligands, which converged on these pathways and results in inflammatory responses and endothelial dysfunction." (PMID 34368262, 2021). "Containing binding and modulating motifs involved in promoting CD36-dependent endothelial dysfunction, this peptide exemplified a mechanistic role for circulating peptides triggering cell-surface receptor mediated systemic effects." (PMID 31142334, 2019). "The increased MV concentrations found in FH patients and the strong association between CD36+ MVs and oxLDL-C in FH with ATX suggest a possible involvement in processes leading to endothelial dysfunction and cardiovascular risk." (PMID 26925191, 2016). "Endothelial dysfunction with diminished vessel compliance was also documented in Cd36−/− mice." (PMID 39503770, 2025). "Over-expression of CD36 promoted Ang II-induced ferroptosis and endothelial dysfunction." (PMID 39595632, 2024). "Whether CD36 has a regulatory effect on endothelial dysfunction has been confirmed in the following results." (PMID 39595632, 2024). "While the results presented in this study firmly support CD36 as a critical receptor mediating the deleterious effects of Tr-OxPLs on lung endothelium, one important question remains unanswered: how do CD36 inhibitors protect against Tr-OxPLs-induced endothelial dysfunction?" (PMID 37566016, 2023). "Considering CD36 as the principal receptor interacting with Tr-OxPLs, we investigated whether the inhibition of CD36 offers protection against Tr-OxPL-mediated endothelial dysfunction." (PMID 37566016, 2023). "Thus, in the cluster of malignant, we speculated that the high expression of Cd36, Lpl, Gpihbp1, Fabp4, and Pparg was important in the metabolism of FAs and may contribute to endothelial dysfunction." (PMID 40440080, 2025). "However, the role of CD36 in mediating the early stages of disease development, i.e., endothelial dysfunction, is unknown." (PMID 38586877, 2024).
endothelial dysfunction (continued). "WT and CD36 knockout (KO) mice were placed on a high-fat, Western diet (42% kcal from fat) for 8 wk, a time point in which robust VAT artery endothelial dysfunction is observed in obese mice." (PMID 38586877, 2024). "Yet, the role of CD36 in the modulation of Tr-OxPLs-induced endothelial dysfunction in relation to the aging process has not been examined." (PMID 37566016, 2023).